LRRC4 (leucine rich repeat containing 4)
Diseases named in the same sentence as LRRC4 in open-access papers (continued):
Sharing a sentence is not in itself a finding about the gene and the disease.
tumor (28 papers, 2008 to 2025). "Immunofluorescence was used to confirm whether the decreased tumour growth observed in mice with LRRC4 overexpression combined with TMZ treatment was associated with an autophagy defect." (PMID 32372061, 2020). "As for the two tumor suppressors Lrrc4 and Sema3b, they were rich in the axon guidance signaling pathway." (PMID 37056757, 2023). "As a tumor suppressor gene, inactivation of LRRC4 mediates DNA hypermethylation in central nervous system tumors." (PMID 35186021, 2022). "We detected high E-cadherin expression in tumor epithelial cells undergoing collective invasive (red circle), but low E-cadherin and Vimentin expression in EOC orthotopic xenograft tumor models with AAV9/GFP/LRRC4." (PMID 32117780, 2020). "As drug resistance contribute to tumour recurrence, we also evaluated the expression of LRRC4 mRNA in GBM and recurrent GBM patients by using the Oncomine Murat brain dataset." (PMID 32372061, 2020). "Here, we focused on the role of LRRC4 in the GBM immune microenvironment by examining tumor tissues, patient peripheral blood and primary GBM cells." (PMID 29312296, 2017). "The data indicates that the expression of LRRC4 is negatively regulated by miR-381 in OS, with miR-381 acting as an onco-miRNA and LRRC4 functioning as a tumor suppressor gene." (PMID 27612424, 2016). "In conclusion, our study indicates that miR-381 functions as an oncogene, and LRRC4 serves as a tumour suppressor gene in OS." (PMID 27612424, 2016). "Our previous studies indicated that LRRC4 gene expression was highly specific to brain tissue, and that the gene product behaved as a tumor suppressor in the pathogenesis of malignant gliomas." (PMID 24404152, 2014). "The central role of EMT in tumor metastasis led us to assess whether it also mediates LRRC4 inhibition of EOC metastasis." (PMID 32117780, 2020). "LRRC4/NGL-2 mediated its tumor suppressor by regulating miR-185 targets CDC42 and RhoA." (PMID 25526788, 2014). "In addition, LRRC4/NGL-2 has been identified as a tumor suppressor gene." (PMID 25526788, 2014). "Our research showed that re-expression of the suppressor gene LRRC4 in GBM cells mediated the interaction between GBM cells and tumor-infiltrating T cells." (PMID 29312296, 2017). "Using this approach, 7 genes were identified as undergoing tumor-specific aberrant promoter methylation in HCC, including IFITM1, SMAD6, TBX15, CHST4, and LRRC4 with hyper-methylated promoters and CCL20 and NQO1 with hypo-methylated promoters." (PMID 26300991, 2015). "Combined LRRC4 expression and TMZ treatment prolonged the survival of mice with tumour xenografts." (PMID 32372061, 2020). "That these genes may also be tumor-suppressor genes in PTC is a novel and interesting finding, as expression of LRRC4 is thought to be restricted to nervous tissue." (PMID 27633254, 2016). "It has been recently shown that LRRC4 binds to phosphoinositide-dependent protein kinase 1 (PDPK1), facilitates activation of NF-κB of GBM cells, and promotes the secretion of IL-6, CCL2 and IFN-γ, and inhibits tumor-infiltrating Treg cell expansion and GBM cell growth." (PMID 33932995, 2021). "Several members, such as LRRC4 and LRRC3B, are either absent or significantly downregulated in various malignancies, suggesting their roles as tumor suppressors." (PMID 40388100, 2025). "We found that 7 genes (IFITM1, SMAD6, TBX15, CHST4, LRRC4, CCL20, and NQO1) showed significantly different promoter methylation levels between tumor and non-tumor tissue (P value < 0.001) in approximately 80 % of the 78 HCCs." (PMID 26300991, 2015). "Experimental design: Eight novel candidate markers, COL4A6, CYBA, TCAF1 (FAM115A), HLF, LINC01341 (LOC149134), LRRC4, PROM1, and RHCG, were selected from Illumina Infinium HumanMethylation450 BeadChip analysis of 21 tumor (T) and 21 non-malignant (NM) prostate specimens." (PMID 28052017, 2017).
tumor (continued). "However, TBX15, LRRC4, and CHST4 showed no systematic difference in expression between HCC and non-tumor liver cell lines." (PMID 26300991, 2015).
cancer (6 papers, 2016 to 2021). A tumor composed of atypical neoplastic, often pleomorphic cells that invade other tissues. "In addition, high-level expression of E-cadherin is also accompanied by the loss of LRRC4 expression in cancer cell clusters in ascites of EOC patient." (PMID 32117780, 2020). "From this list, 8 novel top candidate genes were selected based on their display of highly cancer-specific hypermethylation over multiple adjacent promoter-associated DMCs: COL4A6, CYBA, HLF, LINC0134 (LOC149234), LRRC4, PROM1, RHCG, and TCAF1 (FAM115A)." (PMID 28052017, 2017). "Moreover, LRRC4 ectopic expression reduced cancer cell metastasis to the omentum from ovarian orthotopicallyxenografts." (PMID 32117780, 2020).
metabolic disorders (1 paper, 2025). "To elucidate the mechanism underlying LRRC4 deficiency‐induced metabolic disorders, we utilized KGN cells to establish an LRRC4 knockout model (LRRC4−/− KGN) for in vitro studies." (PMID 40317712, 2025). "We then assessed the impact of YAP on metabolic disorders induced by LRRC4 deletion." (PMID 40317712, 2025).
LRRC4 also shares sentences with these, for which no sentence is quoted: autism (2 papers); Intellectual disability (2); meningioma (2); nasopharyngeal carcinoma (2); Anxiety (1); dermatitis (1); gastric cancer (1); infection (1); kidney cancer (1); osteosarcoma (1); ovarian cancer (1); peripheral nerve lesion (1); pituitary tumor (1); prostate carcinoma (1); psychiatric disorder (1); renal papillary cell carcinoma (1); retinal degeneration (1); skin inflammation (1); viral myocarditis (1).